GFAP (glial fibrillary acidic protein)
Diseases named in the same sentence as GFAP in open-access papers (continued):
Sharing a sentence is not in itself a finding about the gene and the disease.
amyloid (continued). "The lack of GFAP upregulation in the caudate may be due to the fact that this region exhibits amyloid deposition later in the disease stage than cortical regions, thus reflecting a lower level of astrocyte reactivity." (PMID 39580758, 2024). "To assess the relationship between Piezo1 expression and amyloid plaque pathology in adult and aged rats with and without repeated peripheral infections, we correlated Piezo1 fluorescence intensity with both GFAP and Aβ1-42 expression in the dentate gyrus of all groups." (PMID 30405400, 2018). "Furthermore, GFAP-immuno-positive area was significantly reduced in 9-month-old APPKI-SRRKO mice compared with age-matched APPKI mice (p < 0.001), suggesting that endogenous D-serine can also affect astrogliosis and neuroinflammation during the amyloid pathology in APPKI mice." (PMID 37455930, 2023). "Elevations in plasma GFAP and tau PET occurred significantly later than amyloid PET (p = 0.017 and 0.016 respectively) but not plasma pTau‐217." (PMID 39535359, 2025). "Interestingly, we observed that GFAP-negative cells also showed increased expression of Aβ1-42 *(P < 0.05) as well as Aβm0C64 $(P < 0.001), indicating that cells other than astrocytes could also contribute to the process of amyloidosis." (PMID 34527417, 2021). "Total numbers of amyloid plaque and NFTs did not correlate with CHI3L1, CHI3L2, GFAP, and C1q protein levels at any clinical stage." (PMID 32066474, 2020). "Attenuation of astrocytic activation via deletion of GFAP and vimentin in APP/PS1 mice exacerbated amyloid plaque load independent of APP processing and Aβ production, suggesting that astrocytes are important in amyloid clearance." (PMID 24490742, 2014).
Gliosis (109 papers, 2009 to 2026). Gliosis is the focal proliferation of glial cells in the central nervous system. "Proteins regulated by GFAP mAb treatment (depicted in a gradient from yellow to red) were found to interact closely with gliosis-associated proteins." (PMID 40528237, 2025). "This highly complex process is also called reactive gliosis and is caused by the cytokine-mediated activation and proliferation of glial cells, predominantly driven by astrocytes, with upregulation of glial fibrillary acidic protein (GFAP)." (PMID 38539682, 2024). "The immunohistological staining with GFAP to analyze macroglia was performed after six and eight weeks, since retinal degeneration is often associated with gliosis." (PMID 35140707, 2021). "Diffuse and mild levels of gliosis were associated with increased shift to soluble GFAP, until the soluble and insoluble GFAP concentrations were about equal for the patient with the most pronounced gliosis." (PMID 29634780, 2018). "A hallmark of gliosis is the upregulation of intermediate filaments, such as glial fibrillary acidic protein (GFAP), that are in contact with the cytoskeleton and extracellular matrix and will facilitate the rapid and long-term remodeling of tissue structure." (PMID 27483349, 2016). "This may appear to contradict the RFformation with higher levels of GFAP seen in AxD patients and transgenic animals.However, upregulations in GFAP are often associated with gliosis in AxD patients andanimal models." (PMID 30355500, 2018). "Prionopathy associated spongiosis, PrPSc deposition and gliosis (assessed by GFAP immunoreactivity) were evaluated semiquantitatively in the four analyzed brain regions (cSc, Mobl, Cc and Dien) from 6 controls, 4 preclinical and 7 clinical scrapie-infected sheep." (PMID 23497022, 2013). "To reveal whether deficiency in A1 receptors may result in retinal gliosis, we immunostained freshly isolated retinal slices from both mouse strains against the glial intermediate filament GFAP and the major glial Kir channel subtype (Kir4.1)." (PMID 19756184, 2009). "Gliosis was assessed using GFAP and Iba-1 immunohistochemical markers, while neurological deficits were quantified with modified neurological severity scores (mNSS)." (PMID 39851546, 2025). "Gliosis is accompanied by the higher generation of the intermediate filament including GFAP, nestin, and vimentin, which leads to greater and more highly condensed glial processes and fibers." (PMID 38630361, 2024). "Gliosis is a known feature of untreated SD cats as shown by abnormally high levels of the astrocytic marker, GFAP (glial fibrillary acidic protein) and the microglial marker, Iba1 (ionized calcium-binding adaptor molecule 1)." (PMID 39605340, 2024). "Glial fibrillary acidic protein (GFAP) is a marker of gliosis due to the inflammatory response in the retina." (PMID 38915029, 2024). "Müller cells undergo a process of activation, also known as gliosis, which is characterized mainly by an overexpression of intermediate filament proteins, such as GFAP and vimentin." (PMID 36671565, 2023). "Gliosis was evaluated with immunohistochemistry for glial fibrillary acidic protein (GFAP) using an established method." (PMID 36768656, 2023). "Animal models have shown that GFAP expression is altered as a result of SE, and signs of gliosis have been observed in different studies." (PMID 37569895, 2023). "Our data showed that the Aβ1–42 injection prominently activated gliosis, as confirmed by the significantly increased expression level of GFAP and Iba-1 as compared to the normal control group." (PMID 38068844, 2023). "Gliosis in SN exhibits particular features since this region is remarkably richer in microglial cells compared to other midbrain areas, but is poor in glial fibrillary acidic protein (GFAP) positive astrocytes." (PMID 36551173, 2022).
Gliosis (continued). "Gliosis and retinal microglial activation were measured by using GFAP, CD68, and ITGAM mRNA quantification and GFAP, CD68, and Iba1 immunofluorescence stainings." (PMID 35236378, 2022). "Gliosis in the spinal cord is increasingly recognized as a key mechanism of pain chronification, and CD11b and GFAP-expressing levels are generally used as biomarkers for microgliosis and astrogliosis, respectively." (PMID 34575886, 2021). "Gliosis is due to a proliferation of the GFAP-positive processes of Müller cells whereas the excessive number of blood vessels reflects a lost balance between proangiogenic and antiangiogenic factors within the eye environment." (PMID 32581722, 2020). "The changes in the expression of GFAP and vimentin in the tegmentum of chum salmon juveniles are similar to gliosis in mammals; however, scar formation in chum salmon juveniles is weak, which is consistent with data on other fish species." (PMID 31991815, 2020). "This process which is associated with an up-regulation of the intermediate filament GFAP, is known as gliosis." (PMID 31133806, 2019). "Gliosis, as shown by increased GFAP staining intensity, was increased at all anatomical locations in all TBI groups compared to the sham (non-injured) rats as expected in response to this type of traumatic injury for tissue repair." (PMID 30046063, 2018). "In the second analysis, frozen sections were stained with an anti-glial fibrillary acidic protein (GFAP) antibody because gliosis is also a sign of an epileptic hippocampus." (PMID 29313800, 2018). "Markers indicative of gliosis were further investigated by examining patterns of immunoreactivity for GFAP, S100-β, and neurocan (NCAN)." (PMID 28381236, 2017). "Gliosis was evaluated by GFAP (astrocytes) and lectin (microglia) staining in the spinal cord of the EAE-induced mice." (PMID 27196935, 2016). "Gliosis is a common feature of retinal degenerative disease, characterized by enhanced expression of glial fibrillary acidic protein (GFAP)." (PMID 27660801, 2016). "While it is admitted that gliosis is accompanied by an increase of GFAP, detailed kinetic studies performed in our lab have shown that this increase of GFAP expression begins only 2 days after injury." (PMID 26381429, 2016). "Gliosis (GFAP) increased in all regions except the Nac but only PFC was positive for apoptosis (caspase-3)." (PMID 26537106, 2015). "It has been reported that reactive gliosis is a response of astrocytes to a variety of brain insults, characterized by hypertrophy of the cell bodies and processes, and increased GFAP expression." (PMID 25505884, 2014). "Gliosis commonly involves upregulation of the intermediate filament protein, GFAP, in Müller glial cells." (PMID 25301432, 2014). "MPTP treatment resulted in increased GFAP expression, but gastrodin at doses of 10, 30, and 60 mg/kg prevented gliosis dose dependently as shown in the immunoblot and immunofluorescence analyses." (PMID 23533492, 2013). "SE-induced reactive gliosis was also reduced by the 4-day gabapentin treatment, as shown by a reduction in the area immunostained for GFAP astroglial marker, essentially due to the reduced number of astrocytes with shorter projections and smaller soma size." (PMID 24250797, 2013). "Gliosis was more evident in 2-months-old mutant retinas, where a prominent increase of GFAP was observed (arrowheads), mainly at foci of cellular mislocalization." (PMID 24324803, 2013). "The aim of the study described here was to characterize the expression pattern of different GFAP isoforms in WT mice and in the context of AD-related gliosis in transgenic mice." (PMID 22912745, 2012). "Gliosis was morphologically confirmed by GFAP and Iba1 immunostaining." (PMID 41683765, 2026). "Therefore, the upregulation of GFAP in various pathological disorders indicates gliosis, and p-ERK is thought to be involved in Müller cell gliosis." (PMID 40141227, 2025).
Gliosis (continued). "Gliosis was mainly characterised by the presence of reactive astrocytes and by less conspicuous microglial activation, as confirmed by immunohistochemistry for GFAP and CD68, respectively." (PMID 40898647, 2025). "Finally, we investigated the effect of Tib on the expression of glial fibrillary acidic protein (GFAP) and ionized calcium-binding adaptor molecule 1 (Iba-1), two markers of gliosis, using an immunohistochemistry assay." (PMID 40943249, 2025). "Gliosis of Müller cells observed with GFAP in the retina or around the large vessels may be due to the increased vascular permeability associated to hypoxic conditions of COVID-19." (PMID 36855168, 2023). "Gliosis was studied using GFAP and GLAST (coded by the gene Slc1a3)." (PMID 36430480, 2022). "We observed substantial amounts of phosphor-tau proteins (AT8) in brain tissues of Thy1-hTau.P301S mice, and these protein accumulations were accompanied by increased expression of GFAP and Iba-1 (markers of astrocytosis and gliosis, respectively) compared with that in wild-type C57 mice." (PMID 36273169, 2022). "Since candesartan treatment improved behavior and lowered markers of gliosis, we next evaluated whether Iba1 or GFAP immunostaining correlated with memory-relevant behavior (NOR preference index) in combined data from female E4FAD− and E4FAD+ mice." (PMID 33642985, 2021). "Gliosis implies an increased expression of its specific marker, GFAP, in the brain." (PMID 34611142, 2021). "Gliosis is an indicator of glial cell activation, a process that occurs in response to neuroretinal damage, which can be evaluated by Vim and GFAP immunoreactivity in neuroretina cultures, associated with modifications in the intermediate filaments of astrocytes and Müller cells." (PMID 32676122, 2020). "Gliosis was evaluated by GFAP (astrocytes) and IBA-1 (microglia) IHC." (PMID 32023844, 2020). "GFAP is a marker for intermediate filaments in MGCs, and an increase in GFAP occurs in gliosis." (PMID 31438467, 2019). "Statistical analysis across multiple studies showed a high positive correlation (ρ = 0.89, p < 0.05) between device stiffness and normalized GFAP intensity, within a 50-μm band of the device perimeter, indicating that gliosis is more severe when using a stiffer implant." (PMID 30424376, 2018). "Gliosis was quantified by measuring the density of GFAP immunoreactivity." (PMID 29751769, 2018). "Gliosis is accompanied by the emergence of reactive astrocytes and can be determined not only by an increased number of GFAP positive (GFAP+) cells but also by the upregulation of other IFs like vimentin and nestin, as well as a rise of proliferating Ki67 positive cells." (PMID 28841900, 2017). "Gliosis as demonstrated by upregulation of the intermediate filament GFAP." (PMID 28376733, 2017). "In our quantitative analysis of normal cortex, we noted a positive correlation between T2 and gliosis (GFAP) and albumin leakage and T1, suggesting that 9.4T MRI signals may be influenced by subtle reactive cellular changes." (PMID 26268959, 2016). "In accordance to the hypothesis, previous studies have found increased levels of myo-inositol + glycine (Ins + Gly)/creatine (Cre), Iba-1 and GFAP, markers of gliosis, in rodents displaying memory impairment." (PMID 26537106, 2015). "Gliosis based on GFAP increment occurs following the intrastriatal administration of 6-OHDA." (PMID 26090233, 2015). "In another way, GFAP has been widely used is as a molecular marker for gliosis." (PMID 25999851, 2015). "Moreover, GFAP expression is enhanced under pathological conditions that are accompanied by gliosis." (PMID 24816982, 2014). "However, 3-NP administration was unable to significantly change the levels of GFAP (a marker of gliosis) and caspase 3 (a marker of apoptosis)." (PMID 23799154, 2013).
Gliosis (continued). "To assess whether irradiation induces gliosis at 3 months of age, we generated radial sections through the central retina and its proximal optic nerve regions and immunostained them for GFAP." (PMID 22952717, 2012). "Gliosis is characterized as the proliferation and hypertrophy of glial cells and results in upregulation of intermediate filaments, such as glial fibrillary acidic protein (GFAP), vimentine, and nestin, and thickening of large cells." (PMID 23316132, 2012). "Gliosis also includes both proliferation and hypertrophy of GFAP expressing cells." (PMID 20942944, 2010). "The astrocytic marker GFAP (glial fibrillary acidic protein) for gliosis seems to be present in a few narcoleptic patients, and might be found in more since the analyzed tissue had been stored for a long time and could have lost immunoreactivity." (PMID 19721817, 2009). "Similarly, the selective increase in the expression of GFAP in the 15/low performers could indicate that such rats have low performance due to elevated levels of gliosis." (PMID 36091373, 2022). "Indeed, mechanisms of this gliosis can be partially explained by in vitro studies showing that hyperglycaemia leads to mitochondrial oxidative stress in Müller glial cells and induces radial GFAP expression." (PMID 30979946, 2019). "Thus, GFAP may be an effective neurobiomarker for neurological disorders, specifically gliosis." (PMID 37181122, 2023). "We first confirmed that cuprizone induced similar levels of demyelination and gliosis in the Myrf-Het;Nestin-tdT and the Myrf-cKO;Nestin-tdT mice based on MBP and Eriochrome Cyanine stainings, and on GFAP and Iba1 stainings." (PMID 36779010, 2023). "Gliosis and gray-white matter blurring in both FCD types were shown by increased GFAP positivity and irregularly distributed CNPase immunostaining, respectively." (PMID 37006485, 2023). "Gliosis was measured by Iba-1, CD68, and TSPO, markers for microglia, as well as by the astrocytic marker GFAP." (PMID 34948098, 2021). "Regarding the NAWM, previous studies have reported the presence of gliosis in MS patients; however, Graumann and colleagues (2003) did not observe significant differences in GFAP expression between the NAWM of MS patients and control subjects." (PMID 37887329, 2023). "Gliosis was increased in uninjured dorsal root ganglia of PEKO as compared with control mice (green = GFAP, blue = DAPI, red = TuJ1), suggesting that ether lipids derived from the endothelium (as opposed to those generated by neurons) can affect the peripheral as well as the central nervous system." (PMID 33894211, 2021). "Gliosis (GFAP and Iba1) and ER stress markers (pJNK) were not altered in response to dietary intake." (PMID 33202914, 2020). "Despite gliosis is a feature of retinal pathology, our results showed absence of GFAP reactivity in MGCs in ApoE-KO FD mice retinas at 4 months." (PMID 33154969, 2020). "Immunohistochemistry with glial fibrillary acidic protein (GFAP) in the same areas evaluated for PrPSc distribution revealed the presence of gliosis in the experimentally infected animals (data not shown)." (PMID 29795663, 2018). "To determine whether repeated D-amphetamine exposure produced apoptosis or gliosis, we analyzed the levels of PARP [Poly (ADP-ribose) polymerase], cleaved caspase 3, cleaved lamin A/C, and GFAP (glial fibrillary acid protein)." (PMID 28119566, 2016). "Gliosis correlates strongly with neuropathology in LATE-NC and ADNC; we, therefore, hypothesized that a specific interaction between GFAP and Lin bodies would result in greater GFAP presence near Lin body-positive vessels than vessels without Lin bodies." (PMID 38997773, 2024). "However, in contrast to the observed downregulation of ITGB1, GFAP and vimentin, two prototype markers of gliosis, were not changed by modifying glucose levels in RMG." (PMID 34046254, 2021).
Gliosis (continued). "This leads to the conclusion that the generalized link between GFAP and gliosis that we demonstrate here might not always be the case." (PMID 34440226, 2021). "Gliosis (based on a GFAP increase) was identified in the striatum, but not in the SN." (PMID 26090233, 2015). "This may lead to the detection of high GFAP concentrations in psychiatric patients with a gliosis, which may not necessarily be related to the respective psychiatric disease." (PMID 24816982, 2014). "Interestingly, we have found no GFAP and STAT3 positivity in the tumoral areas, though GFAP+ and GFAP+/STAT3+ were highly expressed in areas corresponding to RN and gliosis." (PMID 37762522, 2023).